INS (insulin)
Diseases named in the same sentence as INS in open-access papers (continued):
Sharing a sentence is not in itself a finding about the gene and the disease.
diabetes (continued). "Insulin sensitivity and insulin secretion both exhibit a decline with age, as evidenced by numerous studies in the literature, aligning with the observed rise in diabetes prevalence associated with aging." (PMID 40302958, 2024). "Diabetes is caused by a loss of the physical or functional β‐cell mass, mostly due to an autoimmune process (type 1 aetiological process) and/or increased need for insulin due to insulin resistance (type 2 process)." (PMID 38751247, 2024). "Exercise interventions, whether they be aerobic, resistance training, or both, help diabetic patients not only improve their insulin sensitivity and glucose regulation but also reduce the complications associated with diabetes and enhance quality of life." (PMID 39201202, 2024). "Diabetes mellitus is one of the most common systemic chronic metabolic diseases, mainly manifested by symptoms of hyperglycemia caused by defective insulin secretion and/or insulin function, and it is a serious threat to human health worldwide." (PMID 38205163, 2024). "Insulin resistance in T2D may lead to hyperglycemia with progressive loss of β‐cell function and gradual disappearance of β‐cell insulin secretion, and obesity resulting from a poor lifestyle with a sub‐healthy diet increases the chance of developing diabetes." (PMID 39081515, 2024). "Diabetes is a metabolic disorder that is associated with continuous hyperglycemia and abnormal metabolism of carbohydrates, proteins, and lipids, caused by insufficient insulin secretion, and decreased tissue sensitivity to insulin." (PMID 38233819, 2024). "Type 2 Diabetes Mellitus (T2D) is characterized by elevated blood glucose levels caused by ineffective use of insulin, which may over time damage blood vessels and neurons." (PMID 38815475, 2024). "Diabetes mellitus is a series of metabolic disorders of protein, fat and electrolyte caused by insufficient absolute or relative insulin secretion and reduced sensitivity of target tissue cells to insulin." (PMID 39624687, 2024). "The factors associated with diabetes, such as the accumulation of AGEs, adipokines, insulin, and adiponectin, may also affect the function of TSPCs, contributing to the development of diabetic tendinopathy." (PMID 38633380, 2024). "Diabetes mellitus (DM) in canine and feline is one of the metabolic diseases caused by genetic predisposition and comes along with obesity, where the animals exhibit insufficient insulin secretion and resistance." (PMID 39118186, 2024). "An additional insulin supplementation may be needed in patients with insulin-deficient diabetes, which can further aggravate their body weight." (PMID 38579770, 2024). "In addition, PA is associated with decreased insulin sensitivity and secretion and an increased incidence of metabolic syndrome and type 2 diabetes mellitus." (PMID 39595045, 2024). "Given the established links between reduced peripheral insulin sensitivity and T2D, and between insulin sensitivity and diabetes-associated complications, biological sex is an important variable to consider when studying insulin sensitivity across physiological and pathological contexts." (PMID 38409052, 2024). "Additionally, GDM is recognized as a substantial risk factor for cardiovascular diseases and diabetes in mothers, and it is also linked to obesity and impaired insulin sensitivity in their children." (PMID 38970008, 2024). "Targeting the specific genes involved in metabolic pathways, including glucose metabolism, insulin signaling, and inflammation, may correct the underlying metabolic abnormalities associated with diabetes." (PMID 38931292, 2024). "All patients with type 1 diabetes mellitus (T1DM) require insulin due to its absolute deficiency." (PMID 39734941, 2024).
diabetes (continued). "It is important to highlight that the primary abnormality of insulin response, the early presence of beta cell dysfunction, can also be associated with a significantly increased risk of gestational diabetes mellitus and subsequent diabetes mellitus." (PMID 38337532, 2024). "Unbalanced insulin release would easily cause hypoglycemia or hyperglycemia in diabetes." (PMID 38751366, 2024). "Diabetes mellitus (DM) is a chronic, endocrine, and metabolic condition characterized by elevated glucose levels and linked to the disruption of carbohydrate metabolism, either due to insufficient insulin production or a failure of the utilization of insulin." (PMID 39123629, 2024). "Type 1 diabetes mellitus (T1DM) arises due to an autoimmune response wherein the body specifically attacks the insulin-secreting cells, whereas type 2 diabetes mellitus (T2DM) is caused by an imbalance between the production of insulin by beta cells and its efficacy, resulting in insulin resistance." (PMID 39403720, 2024). "Diabetes diagnosis and insulin sensitivity have been linked to COVID-19 severity and mortality, and downregulated ERRa in our COVID-19 cohort is linked to insulin resistance, diabetes, and obesity." (PMID 38760690, 2024). "In addition, some SNPs of SMEK1 were also associated with diabetes, insulin homeostasis, body weight, and other phenotypes." (PMID 38568153, 2024). "Furthermore, the reduction in body weight in diabetes has been associated to excess protein tissue destruction, dehydration and decreased insulin production." (PMID 39070783, 2024). "The Diabetes Control and Complications Trial showed that maintaining excellent glycemic control with intensive insulin therapy significantly reduced the risk of early microvascular complications of diabetes by an average of 6.5 years compared to conventional treatment." (PMID 38542165, 2024). "Overall, the evidence suggests that while sucralose may slightly affect insulin sensitivity, the overall impact of ASs on diabetes risk remains inconclusive." (PMID 39449954, 2024). "Additionally, mice with insulin-deficient diabetes were given miR-106b/222 through IV, which increased β-cell growth and improved high blood sugar." (PMID 38455849, 2024). "Excessive accumulation of selenium in the body may cause oxidative stress by interfering with cellular redox processes, which may directly or indirectly disrupt insulin metabolism, leading to insulin resistance and an increase the risk of diabetes mellitus." (PMID 37996718, 2024). "In subjects with diabetes, particularly those receiving insulin therapy, these alterations may increase the risk of the deterioration of glycemic control." (PMID 39203800, 2024). "Several studies have shown that, among relatives of individuals with type 1 diabetes, predictors of progression to diabetes include high-risk HLA genotypes, age at autoantibody seroconversion, increasing numbers of positive AAbs, and dysfunctional glucose-stimulated insulin secretion." (PMID 37914981, 2024). "This suggests that blueberry polyphenols may improve insulin sensitivity and mitigate pancreatic β-cell damage associated with diabetes." (PMID 39765819, 2024). "For example, certain diseases are bad outcomes for the treatment of specific diseases (e.g., clozapine and olanzapine, used for treating psychiatric disorders, can lead to insulin sensitivity and lipid metabolism changes, which increase the risk of diabetes and cardiovascular disease)." (PMID 38753827, 2024). "Additionally, this study highlights a potential association between altered insulin signaling, protein expression patterns, and tumor progression, particularly in patients with diabetes." (PMID 38731981, 2024). "Altogether, our results lend support for statewide Medicaid policymakers to expand Medicaid coverage of CGMs for people with T2DM on once-daily insulin per American Diabetes Association guidelines especially given that such an access expansion is projected to be highly cost-effective." (PMID 38974988, 2024).
diabetes (continued). "Insulin resistance and related increased plasma insulin levels (hyperinsulinemia) may cause metabolic impairments, which are pathological states observed in obesity and type 2 diabetes mellitus." (PMID 38392069, 2024). "Any abnormality in the production or consumption of insulin can cause diabetes." (PMID 39035597, 2024). "The link between diabetes and insulin is undeniable and intrinsically causal." (PMID 39280004, 2024). "A number of factors as a result of hyperglycemia and/or insufficient intracellular insulin signaling due to insulin resistance or insulin deficiency, which are the major features of diabetes, have an adverse impact on renal cell health, and can cause cell death in the kidney." (PMID 39139135, 2024). "Caffeinated drinks might contribute to diabetes risk through their potential to affect insulin sensitivity or promote unhealthy dietary habits." (PMID 38603719, 2024). "Mechanistic links have been established between vitamin D, insulin secretion, insulin sensitivity, and inflammation, which may explain the correlation between vitamin D status and diabetes risk." (PMID 38525711, 2024). "Diabetes is often associated with cognitive decline and shares similar pathophysiological mechanisms with dementia, such as systemic inflammation, oxidative stress, insulin resistance, and advanced glycation end-products formation." (PMID 39200215, 2024). "The connection between stroke and insulin therapy, a novel aspect, is discussed, noting it may be linked to either insulin therapy or uncontrolled diabetes." (PMID 39295783, 2024). "In fact, sustained lowering FAs levels achieved with long-term therapy Acipimox was shown to increase insulin secretion rates in a subset of patients with diabetes or at risk of diabetes, suggesting that FFAs homeostasis is important for insulin secretion regulation, especially in people at risk." (PMID 38642584, 2024). "Additionally, flavonoids found in dried fruits have been associated with improved insulin sensitivity and glucose metabolism, which are key factors in managing diabetes." (PMID 38987806, 2024). "Insulin treatment is associated with a poor prognosis in patients with COVID-19 and diabetes." (PMID 38755442, 2024). "It has been reported that exercise could control blood sugar, increase insulin sensitivity, lose weight, reduce cardiovascular risk factors, and improve life well‐being in diabetes." (PMID 38617433, 2024). "It was initially thought that insoluble fibre may reduce the risk of diabetes through the production of short-chain fatty acids in the colon and their effects on hepatic insulin sensitivity." (PMID 38337719, 2024). "It has been documented that insulin‐treated rats had increased astrocytic GFAP as compared to diabetic rats; therefore, insulin is of great importance in improving the function of astrocytes, the dysfunction of which is implicated in the CNS complications of diabetes." (PMID 38639646, 2024). "After adjusting for maternal age, duration of diabetes, BMI, and daily dose of insulin, CSII therapy was associated with elevated risks of neonatal jaundice (adjusted odds ratio [aOR] 2.76, 95% confidence interval [CI] 1.16–6.57), and NICU (aOR 3.73, 95% CI 1.24–11.16), compared with the MDI group." (PMID 38664886, 2024). "Low serum potassium may be a disturbing factor for insulin secretion and cause glucose intolerance or diabetes." (PMID 38612580, 2024). "Diabetes mellitus (DM) is metabolic disorders characterized by hyperglycemia, that may occur due to complete or partial deficiency of insulin." (PMID 39723034, 2024). "Other potential contributing variables may include insulin secretion deficiencies, mitochondrial damage, systemic metabolic abnormalities, persistent inflammation, and other diabetes-related problems." (PMID 38643133, 2024).
diabetes (continued). "Moreover, Selective serotonin reuptake inhibitors, insulin and metformin, which are recommended for treating diabetes mellitus‐induced depression, were found to be a risk factor in some complications of diabetes." (PMID 37927197, 2024). "Notably, TCF7L2′s ability to modulate PIK3R1 expression suggests its involvement in insulin signaling pathways, potentially mediating diabetes risk through interactions with KLF-14." (PMID 38672763, 2024). "In the UKPDS (United Kingdom Prospective Diabetes Study), the administration of metformin to overweight patients with type 2 DM reduced the risk of stroke compared to treatment with sulphonylureas or insulin (p = 0.032)." (PMID 39407846, 2024). "Development of diabetes in patients with the heterozygous pathogenic variant R46Q is likely explained by a combination of lower receptor binding affinity of the secreted GlnB22-insulin and some degree of impaired beta cell function." (PMID 39027635, 2024). "Moreover, the unique heterogeneity of diabetes phenotypes suggest that Asian Indians are more commonly comprised of severe insulin-deficient phenotypes than other populations." (PMID 38668336, 2024). "Type 1 diabetes mellitus (T1DM) is caused by an absolute low level of insulin." (PMID 39076511, 2024). "Below this threshold, individuals may show enhanced insulin sensitivity and lipid profiles, thereby reducing the risk of diabetes development." (PMID 39175577, 2024). "Myo-inositol is a sugar alcohol containing six carbon atoms that helps improve insulin sensitivity, and its deficiency may be related to the pathogenesis of metabolic diseases, such as metabolic syndrome, polycystic ovary syndrome, and diabetes." (PMID 38558794, 2024). "Therefore, medication adherence, proper regimen compliance, and correct storage and usage of insulin and associated devices, are considered critical factors for the management of diabetes." (PMID 38476498, 2024). "Hyperlipidemia, impaired insulin signaling, low levels ofinsulin-like growth factor 1, reactive oxygen species generation, andinflammation are all linked to diabetes and hyperglycemia, and may all contributeto the inhibition of osteoblast activity." (PMID 39742238, 2024). "Conversely, inappropriate delay of insulin therapy may cause glucolipotoxicity and diabetes-related complications." (PMID 39252700, 2024). "A low disposition index may indicate either beta-cell decompensation in the face of insulin resistance or the presence of a genetic disorder affecting insulin secretion, potentially involving variants in monogenic diabetes genes." (PMID 38550917, 2024). "National pump audit data in the UK from 2017 to 2018127 and from 2019 to 2020128 reports an inverse relationship between the use and access to insulin pump therapy with socioeconomic quintile, and in T1D care, lower socioeconomic status is associated with poorer diabetes‐related outcomes." (PMID 39291355, 2024). "The increased presence of Akkermansia muciniphila is suggested to reduce the risk of metabolic diseases such as obesity and diabetes, as indicated by previous research, contributing to maintaining a healthy body weight through appetite regulation and improved insulin sensitivity." (PMID 38539873, 2024). "Diabetes may cause dysregulation of Smad3 and Tgfb, two crucial regulators of insulin gene transcription and β-cell function." (PMID 38884019, 2024). "Thus, impaired insulin secretion is greatly associated with the pathology of diabetes in Asians, including Japanese people." (PMID 38839813, 2024). "However, in conditions such as diabetes, where there is hyperinsulinemia and insulin resistance, this can impact the brain insulin sensitivity, resulting in a loss of the normal dynamic regulation of brain cholesterol production." (PMID 39518747, 2024). "Supplementing with omega-3 fatty acids can improve insulin sensitivity, reduce inflammation, and may reduce the risk of developing diabetes." (PMID 38612580, 2024).
diabetes (continued). "The risk of ketoacidosis was low and mainly among patients with diabetes on insulin at baseline." (PMID 38061372, 2024). "Diabetes in patients with the heterozygous pathogenic variant R46Q in the insulin gene is probably explained by a combination of lower receptor binding affinity of the mutant insulin and some degree of impaired beta cell function." (PMID 39027635, 2024). "The use of Gla-100 based insulin analog regimens in diabetes individuals with eGFR <90 mL/min was associated with significantly increased eGFR (+5.45 mL/min; P = 0.04) and a lower urinary ACR (ratio logarithm -0.67; P = 0.004) when compared to HI as a reference." (PMID 36896906, 2024). "Adropin—a multifunctional peptide with tissue-protective capacity that regulates energy homeostasis, sensitivity to insulin and inflammatory response—seems to show an inverse association with the presence of cardiovascular and renal diseases, obesity and diabetes mellitus in the general population." (PMID 39200321, 2024). "This gap between our results and previous studies reporting the fasting insulin association with stroke risk could arise because people with a high fasting insulin level in previous studies could have had undetected diabetes." (PMID 39347227, 2024). "The moderating effect of MDS was significant in people with diabetes and people with BMI ≥25 kg/m2 may be associated with insulin and glucose metabolism due to the role of magnesium in insulin and glucose metabolism." (PMID 38895658, 2024). "This indicates that diabetes reduces the retinal ceramide content and may suggest that dysregulated sphingolipid metabolism may cause retinal resistance to insulin action." (PMID 38741137, 2024). "In addition, the systemic inflammation associated with infection can disrupt insulin regulation, leading to insulin resistance and increased glucose levels, therefore, this suggests a bidirectional association between diabetes/glycemia and COVID-19." (PMID 38533301, 2024). "Previous studies have shown that women have lower insulin sensitivity than men of the same age, which may make women more vulnerable to insulin resistance, thus increasing the risk of diabetes." (PMID 38390200, 2024). "Although these changes are compensatory mechanisms necessary for β-cell survival, in β cells of individuals susceptible to diabetes, these stresses might result in decreased insulin secretion and increased apoptosis, leading to impaired glucose tolerance." (PMID 38188453, 2024). "In relation to the results obtained in the lipid profile, is well known that defects in insulin action or hyperglycemia could be associated with changes in plasma lipid/lipoprotein metabolism in patients with diabetes." (PMID 38892601, 2024). "Especially in women with type 1 diabetes mellitus the risk of hypoglycemia is high in early pregnancy, but it decreases with the progression of pregnancy due to hormonal changes causing an increase of insulin resistance." (PMID 37101033, 2023). "As we have described in this review, mitochondrial disease may cause diabetes via insulin secretory defects and/or IR." (PMID 36671511, 2023). "The aim of the study was to evaluate if diabetes status, duration of diabetes and insulin use could be risk factors for the development of several types of cancer." (PMID 38146457, 2023). "However, HFD mice lack a translational prediabetic state, and rarely develop overt diabetes with loss of insulin release and unchecked hyperglycemia." (PMID 37233701, 2023). "Particularly for SMS, a few medical reports have indicated that alterations of both basal glucose and insulin can be frequently found with a potentially increased risk of developing diabetes mellitus type 2, insulin resistance, and metabolic syndrome during adulthood." (PMID 37761412, 2023).